HIF1A (hypoxia inducible factor 1 subunit alpha)
Diseases named in the same sentence as HIF1A in open-access papers (continued):
Sharing a sentence is not in itself a finding about the gene and the disease.
diabetes (continued). "Hypoxia-inducible factor-1α (HIF-1α), a transcription factor essential for the cell’s adaptive responses to hypoxia, serves as a central molecular mediator linking OSA to the development of diabetes mellitus." (PMID 41155523, 2025). "The results suggest that LOX, HIF1α, THBS1, TGFβ2, and ITGβ1 may be involved in the diabetes‐induced downregulation of FGF9, thus promoting the development of renal EMT." (PMID 40977522, 2025). "For instance, HIF-1α inhibitors like PX-478 have demonstrated improvements in β-cell function within diabetic models, underscoring the therapeutic potential of modulating HIF-1α in diabetes and its complications." (PMID 40867634, 2025). "HIF1A, a hypoxia-inducible factor, was found to play an essential role in activating the transcriptional cofactor FOG2 in a CMVD mouse model of mild hypertension–diabetes injury, a condition relevant to human disease." (PMID 39272451, 2024). "Although high glucose inhibits the HIF-1α response and the expression of VEGF, at the same time, the continuous existence of glucose metabolism disorder in diabetes means that the hypoxia factor cannot change and still stimulates the expression of HIF-1α and VEGF." (PMID 37251664, 2023). "Based on our knowledge, no studies have evaluated the role of HIF-1α in diabetes-induced testicular dysfunction." (PMID 36778206, 2023). "In this context, HIF-1α stabilization by inhibiting SET7/9 function and antagonizing HIF-1α methylation thus becomes a possible strategy to promote angiogenesis to enhance wound healing in diabetes." (PMID 35859119, 2022). "Our results uncovered that AS-IV can protect retinal cells against diabetes induced retinopathy, which may act on target proteins AKT1, CASP3 and HIF1α, VEGFA, IL6, IL1β, SRC and CTNNB1, and might be involved in the regulation of PI3K-AKT signaling pathway." (PMID 35814228, 2022). "We reported that activation of HIF1α–PFKFB3 in rodent models of prediabetes preceded chronic glycolytic energy production, which further exacerbated the slip of β-cells into decompensation and diabetes progression." (PMID 35318430, 2022). "Hypoxia is greatly associated with human physiology and pathophysiology, with a critical HIF1α function in these processes, but the role of HIF1α in the pathogenesis of diabetes is not obvious." (PMID 35328751, 2022). "Human β-cells with a HIF1α signature (based on lactate-dehydrogenase, LDHA expression) from single-cell RNA sequencing (sc RNA Seq) analysis resembled double-insulin- and glucagon-positive cells in our mouse model of diabetes." (PMID 35318430, 2022). "Three of these coding genes (BCL2, HIF1A, and TIMP3) were common genes in diabetes and DR." (PMID 34707685, 2021). "In the current study, activation of cardiac NNCS prevented the reduction in coronary vessels in the heart at the later stage of diabetes, which is likely through the activation of PI3K/Akt/ HIF1α signaling cascade and its downstream target pro-angiogenic VEGF as previously demonstrated." (PMID 33618724, 2021). "However, it is at odds with the finding that, under hypoxic conditions, HIF-1α was inhibited by HG in renal proximal tubular cells, suggesting an impaired HIF-1α-dependent response to hypoxia in diabetes." (PMID 34572324, 2021). "In diabetes, multiple tissues are hypoxic but adaptive responses to hypoxia are impaired due to insufficient activation of HIF signalling, which results from inhibition of HIF-1α stability and function due to hyperglycaemia and elevated fatty acid levels." (PMID 33496820, 2021). "Further evidence of the potential importance of HIF-1α is derived from studies investigating factors related to the inhibition of HIF-1α, osteoclastogenesis, and aneurysm formation, such as female sex and diabetes." (PMID 31546645, 2019). "Ldha expression was significantly decreased in both diabetes-exposed and non-exposed Hif1a+/− hearts." (PMID 29753320, 2018).
diabetes (continued). "Hyperglycemia upregulates HIF-1α in the glomeruli of diabetic model mice regardless of the etiology of the diabetes." (PMID 28774305, 2017). "Since HIF-1α is capable of increasing transcription of profibrotic genes, it can greatly contribute to the renal fibrosis in diabetes with or without hypoxia leading to end-stage renal failure." (PMID 28164134, 2017). "Secondly, as type 2 diabetes is the most common form of diabetes, accounting for more than 90% of all cases, it is of great importance to further investigate the potential role of DATS and AMPK-mediated AKT/GSK-3β/HIF-1α signaling pathway under type 2 diabetic condition." (PMID 29088824, 2017). "In addition, betaine treatment alleviated diabetes-induced vascularization by suppressing VEGF and HIF-1α expression via downregulation of pAkt expression in the retina of the STZ-induced diabetic rats." (PMID 25891515, 2015). "This diabetes-induced IRS2 downregulation could, by means of inhibiting the Akt-mTOR axis, contribute to the observed reduction in HIF-1α total protein level." (PMID 25381014, 2015). "Consistent with a negative effect of diabetes on HIF-1α function, decreased levels of one of the best-known HIF-1 targets, VEGF-A, have been detected in diabetic hearts and other tissues." (PMID 24502509, 2014). "In our study, HIF-1α correlated with some cardiovascular risk factors (CRP, IL-6, UKPDS, HbA1c and FBG), but were not correlated with others (diabetes duration, age and LDL)." (PMID 24564828, 2014). "Five weeks after diabetes was established, a significant decrease in left ventricle fractional shortening was detected in diabetic Hif1a+/- but not in diabetic Wt mice." (PMID 24502509, 2014). "HIF-1α levels positively correlated with CRP, IL-6, UKPDS risk score, HbA1c, FBG, and CACS, but did not correlate with diabetes duration, age, and LDL." (PMID 24564828, 2014). "Unexpectedly, HIF-1α levels were significantly increased in diabetes-exposed Hif1a+/- hearts compared to diabetes-exposed Wt and non-diabetic Hif1a+/- mice by 2.6-fold and 2.1-fold, respectively." (PMID 24502509, 2014). "Surprisingly, we observed an increased number of apoptotic cells in the diabetes-exposed Wt hearts but not in the Hif1a+/- hearts." (PMID 24502509, 2014). "This is in line with other reports showing that diabetes-reduced VEGF-A expression is the result of decreased HIF-1α functional activity but not HIF-1α stabilization." (PMID 24502509, 2014). "Further, we hypothesized that enhancement of endogenous myocardial HIF-1α is a key mechanism whereby antioxidants NAC and ALP confer synergistic cardioprotection against myocardial IRI in diabetes." (PMID 23874823, 2013). "Simultaneous measurement of HIF-1α, HIF-3α, and HIF1-AS1 expression may serve as a reliable model for early prediction of COVID-19 severity, especially in patients with comorbidities such as diabetes and obesity." (PMID 40702494, 2025). "We detected the levels of HIF-1α in diabetic kidneys, and the results showed that although there was no obvious difference in HIF-1α levels between the control group and the model group, the levels of HIF-1α in diabetic kidneys increased after treating with JCYSTLF." (PMID 38720731, 2024). "Upstream regulator analysis suggested COMMD1, HIF1A, EGLN, PIK3R1 and MTORC1 as major upstream regulators for the phase shifts, while HSP90B1, YWHAZ, CNGA3, COL2A1 and TFRC were identified as the major upstream regulators for the amplitude changes observed in the diabetic retina." (PMID 38039846, 2024). "In vitro, the expression of HIF-1α and JMJD1A in ECs was upregulated by high glucose and hypoxia in the present study, indicating that the two may serve as important factors of endothelial dysfunction in diabetes." (PMID 34479471, 2021).
diabetes (continued). "The HIF-1α/JMJD1A pathway might act as a novel regulator of oxidative stress and inflammatory-related events in response to diabetic vascular injury, thus contributing to the pathological progression of diabetes and vascular disease." (PMID 34479471, 2021). "Thus, we hypothesized that RR-CO might regulate glycolysis of testicular cells to improve diabetes-induced reproductive damage by influencing the levels and activities of AGEs, RAGE, and HIF-1α." (PMID 34262451, 2021). "In our study, we found increased levels of both Hif-1a and VEGF-A in diabetes, which may imply that in diabetes early vascular dysfunction and decreased blood flow generate a hypoxic milieu that may be the initial incentive for enhanced cerebral microvasculature." (PMID 34305641, 2021). "Here we demonstrated that modulation of HIF-1α might be involved in MG-induced ROS formation and functional impairment in brain ECs, and HIF-1α modulation may be a preventive strategy in patients with diabetes to reduce cardiovascular complications." (PMID 32899154, 2020). "Whareas, the function and the mechanisms of ginsenoside Re against diabetes-induced retinal injury remain unclear, and the mechanisms have not been determined via the HIF-1α/VEGF signal pathway." (PMID 32528282, 2020). "Refer to the past research of HIF-1α in diabetes complications including DR, HIF-1α has become a potential target, and the research of new drugs for treatment of DR will be of great significance for patients suffering from diabetes and its related chronic complications." (PMID 32528282, 2020). "In addition, alteration of MMPs-9, −13 and −14 expression, PARP-1, HIF1α, and increased collagen biosynthesis as well as collagen cross-linking protein, P4HA1 and PLOD2 were observed along with diminished vascular density in diabetic kidney." (PMID 28883608, 2017). "Moreover, in addition to hypoxia, other factors such as angiotensin II, TGF-β1, PKC, and ROS which are found to be upregulated in diabetes can also activate HIF-1α, thereby exacerbating glomerular injury even in nonhypoxic condition." (PMID 28164134, 2017). "For instance, among the noxious effects of HIF-1α, which is related to our experimental setting, it is worth mentioning that hypoxia-dependent increased tubular activity of HIF-1α has been proposed as a contributing factor in the development of tubulointerstitial fibrosis in diabetes mellitus." (PMID 23984430, 2013). "Another intriguing example is HDAC4, which may deacetylate hypoxia inducible factor 1 subunit alpha (HIF‐1α) that upregulates vascular endothelial growth factor A (VEGFA), which consequently leads to suppression in osteogenic precursor cells differentiation and aggravate diabetic OP in mice." (PMID 40170748, 2025). "Indeed, the present study demonstrated that activating the HIF-1α pathway in osteoblasts by knocking out Vhl in osteoblasts or activating the bone tissue hypoxia pathway through SF-DFO promoted bone formation and partially reduced diabetes symptoms induced by STZ." (PMID 38945950, 2024). "HIF-1α levels positively correlated with CRP (r = 0.226, P = 0.023), IL-6 (r = 0.316, P<0.001), UKPDS risk score (r = 0.144, P = 0.009), HbA1c (r = 0.242, P<0.001) FBG (r = 0.244, P = 0.029), and CAC scores (r = 0.360, P<0.001), but did not correlate with diabetes duration, age, and LDL." (PMID 24564828, 2014). "Unlike HIF-1α, there are relatively a few papers reporting a role of HIF-2α in insulin signaling and diabetes." (PMID 37072781, 2023). "Five weeks after diabetes was induced by repeated intraperitoneal STZ injections, the body mass and LV mass gains of diabetic Hif1a+/- and Wt males were lower compared to non-diabetic groups." (PMID 24502509, 2014). "Currently, some evidence suggests that an imbalance in the HIF-α isoforms (elevated HIF-1α and/or reduced HIF-2α) may contribute to the development and progression of cardiovascular and renal complications of diabetes, although direct proof is lacking." (PMID 36358555, 2022).
diabetes (continued). "Unlike HIF-1α, there are only a few studies focused on HIF-2α in diabetes." (PMID 35798726, 2022). "Although the allicin treatment prevented the increase in HIF-1α and VEGF in comparison with the diabetic group, this treatment further increased Epo and Epo-R without statistical difference between both groups of diabetes." (PMID 33203103, 2020).
ischemia (207 papers, 2010 to 2026). A hypoperfusion of the BLOOD through an organ or tissue caused by a PATHOLOGIC CONSTRICTION or obstruction of its BLOOD VESSELS, or an absence of BLOOD CIRCULATION. "HIF-1α, a key element in regulating oxygen homeostasis, is mainly associated with hypoxia-related diseases (such as ischemia, pulmonary hypertension, and cancer) and the pathogenesis of inflammation." (PMID 36814597, 2023). "Curcumin is able to suppress the excessive upregulation of HIF-1α, mitigating cell injury caused by ischemia." (PMID 37021057, 2023). "To mimic mild and severe ischemia, we activated HIF-1α in HK-2 cells in nutrient-replete or nutrient-deficient conditions." (PMID 36139884, 2022). "It was demonstrated using partially HIF-1α-deficient mice in intestinal ischemia/reperfusion (I/R) injury model that HIF-1 activation played a substantial role in the mechanism of intestinal injury, leading to the loss of barrier function." (PMID 36430628, 2022). "Accordingly, compared to wild-type animals, those with Hif-1α/Hif-2α deficiency exhibited preserved neurological status and sensorimotor functions on the first day after ischemia/reperfusion, but more severe symptoms after 72 h." (PMID 34395432, 2021). "For instance, it was reported that HIF-1α increased apoptosis that led to ischemia-induced delayed neuronal death and HIF-1α deficiency reduced ischemia damage." (PMID 34336097, 2021). "Hypoxia inducible factor-1α (HIF-1α) is stabilized under hypoxic conditions as found during transplantation associated ischemia and has been shown to be activated by mTOR21." (PMID 34381142, 2021). "Statistical analysis revealed that the percentage of HIF-1α immunoreactive cells was significantly associated both with disc area (oAF, iAF, NP) and disc level (control and ischemia discs) at 4 weeks after the ligation of lumbar arteries (p < 0.05)." (PMID 31351455, 2019). "In conclusion, HTK solution maintained high HIF-1α levels in a neurological cell ischemia study, associated with increased procaspase-3 production, suppressed procaspase-3 activation, and decreased NOX4 expression." (PMID 31504040, 2019). "Although potentially beneficial in ischemia, the upregulation of the HIF-1α transcription factor has been linked to inflammation and oxidative stress occurrence." (PMID 25613908, 2015). "Tissue protection by xenon preconditioning and treatment has been associated with an up-regulation of HIF-1α in several in vivo and in vitro models of ischemia." (PMID 25671080, 2014). "Neuron-specific knockouts of HIF-1α to hypoxic-ischemic damage in a global mouse ischemia model suggested that decreasing the level and loss of the proapoptotic function of HIF-1α could be neuroprotective." (PMID 25229058, 2014). "Furthermore, HIF-1α inhibition by the chemical compound YC-1 has been shown to increase damage after stroke while simultaneously inhibiting ischemia induced vascular leakage, normally associated with smaller tissue damage." (PMID 24409307, 2014). "Thus we suggest that in post-OGD neurons the high level of HIF-1α might be due to Pin1 binding ability and activity reduction which affects HIF-1α degradation: an event that may highlight the relevance of ischemia/HIF-1α as a risk factor in AD pathogenesis." (PMID 24478626, 2014). "In conclusion, HIF-1α acts as a “double-edged sword” during ischemia: it is protective in transient ischemia by inhibiting apoptosis, but detrimental during prolonged and irreversible injury by promoting inflammation." (PMID 41602837, 2026). "A recent study has shown that PM2.5 exposure upregulates HIF-1α in mouse myocardium, leading to myocardial injury and hypertrophy, as well as in an in vitro hypoxia-ischemia model using H9c2 cells." (PMID 40149705, 2025). "A recent study found that timely activation of HIF-1α in astrocytes in the early stages of ischemia and enhancement of ischemic tolerance in astrocytes can improve the prognosis of acute ischemic stroke." (PMID 39926015, 2025).